IL10 (interleukin 10)
Diseases named in the same sentence as IL10 in open-access papers (continued):
Sharing a sentence is not in itself a finding about the gene and the disease.
Obesity (continued). "Therefore, IL-10 treatment could be a potential therapy to obesity-related renal failure." (PMID 33547567, 2021). "In our study, we saw a significant increase in the expression of TNF-α, resistin, and IL-10 by adipocytes isolated from ING and RP depots, as a consequence of the HF diet-induced obesity." (PMID 33652751, 2021). "Hence, it is possible that gAd/AdipoR1 axis may exert a protective role against inflammatory conditions, such as obesity, where the upregulation of AdipoR1 through its own ligand may increase the sensitivity of Tregs to adiponectin, which in turn promotes IL-10 production." (PMID 34084174, 2021). "NF-κB pathway and proinflamatory cytokines such as IL-10, IL-6, and TNF-α promote inflammation and exacerbate obesity." (PMID 34812408, 2021). "RASE1 suppressed the NF-κB pathway and proinflammatory cytokines IL-10, IL-6, and TNF-α levels in mice which involve inflammation and progression of obesity." (PMID 34812408, 2021). "After an obesity-induced IR model in mice was constructed, both TGF-β1 and IL-10 protein expressions were downregulated but those of IL-17 and IL-6 were upregulated (P < 0.001)." (PMID 33781239, 2021). "In our study, neither SV nor SPL ablation promoted significant alterations in IL10 plasma levels or IL10 expression in WAT from M-Obese rats, suggesting that the vagal-splenic circuits are interrupted in obesity." (PMID 34248663, 2021). "RASE1 suppressed NF-κB, pathway and proinflammatory cytokines IL-10, IL-6, and TNF-α level, which are involved in inflammation and progression of obesity." (PMID 34812408, 2021). "Moreover, obesity can modulate other T-cell subsets such as T-regulatory (Treg) cells which function as immunosuppressant cells and when down regulated in obese patients, they can reduce production of interleukin-10 (IL-10) which leads to exacerbation of the chronic inflammatory state." (PMID 33194687, 2020). "In the present study, we examined the effects of interleukin (IL)-10 expression-inducing bacteria Bifidobacterium adolescentis HP1, Lactobacillus mucosae HP2, and Weissella cibaria HP3 on high-fat diet (HFD)-induced obesity and liver steatosis in mice." (PMID 31986244, 2020). "For that purpose, we focused on IL‐6, IL‐10, and TNF‐α, key pro‐ and anti‐inflammatory cytokines known to be dysregulated in obesity." (PMID 32614494, 2020). "Unlike B2 cells, tolerogenic B1a cells are reduced in frequency during obesity and produce less IL-10 and transferring B1a cells from lean mice into HFD-fed B null mice can improve metabolic parameters through IL-10- and polyclonal IgM-dependent mechanisms." (PMID 32499756, 2020). "The expression of IL-10, CD36, TLR2, and HSP70 (stress and/or obesity-related genes) was significantly upregulated in overfed fish." (PMID 32854279, 2020). "Since this study found a correlation between the deltas of IL-10 and ASC, in this context, ASC is suggested as the possible regulatory molecule between exercise, Treg cells, obesity, and inflammation." (PMID 32854610, 2020). "SLKDT intervention significantly inhibited obesity‐induced inflammation by decreasing the proinflammatory factors IL‐6, TNF‐α, IFN‐γ, and IL‐1β and increasing the anti‐inflammatory cytokines IL‐4 and IL‐10." (PMID 32884731, 2020). "On the contrary, anti-inflammatory adipokines such as adiponectin, IL-10, and secreted frizzled-related protein 5 (SFRP5) are downregulated in obesity." (PMID 31475003, 2019). "In contrast, peritoneal macrophages displayed TNF-α/IL-10 ratios that were intermediary to AT-SVF and alveolar macrophages, and, unexpectedly, assumed a less pro-inflammatory cytokine response to LPS in obesity." (PMID 31316525, 2019). "The following variables were significantly associated with the IL‐18 concentration at three out of the four occasions during follow‐up: male sex, obesity, diabetes and biomarkers of renal function (cystatin C), and inflammation (WBC, CRP‐hs, GDF‐15, Il‐10)." (PMID 31596518, 2019).
Obesity (continued). "We identifed indigo, an aryl hydrocarbon receptor (AhR) ligand agonist, as a potent inducer of IL-10 and IL-22, which protects against high-fat diet (HFD)-induced insulin resistance and fatty liver disease in the diet-induced obesity model." (PMID 30944419, 2019). "Within this range of M1 polarity, the adipose tissue (AT-SVF) macrophages had the lowest TNF-α/IL-10 ratios, and switched their cytokine response to LPS to a more pro-inflammatory profile in HFD-induced obesity." (PMID 31316525, 2019). "This study also identified IL-6 and IL-10 as markers of TLR4 activation in HCC and subjects with NAFLD and obesity as the target population who would benefit from TLR4 inhibition treatment for HCC chemoprevention." (PMID 30034633, 2018). "In this study, we evaluated the role of cytokines in T2DM and obesity by measuring plasma TNF-α, IL-6, and IL-10 levels." (PMID 28225860, 2017). "To further investigate the molecular mechanism responsible for TMAO-induced cardiac fibrosis and dysfunction in WD-induced obesity, we measured the protein levels of pro-inflammatory cytokines TNF-α and IL-1β and anti-inflammatory cytokine IL-10 in the hearts." (PMID 28377725, 2017). "Therefore, our results highlight that PhyS-milk consumption may induce a shift towards a decreased inflammatory state through its effect on two key cytokines, CCL2/MCP-1 and IL-10, having thus a potential effect in the context of obesity where inflammatory pathways are exacerbated." (PMID 28608804, 2017). "For example, in the murine High-Fat diet induced model of obesity, treatment of mice with LNFPIII-NGC alleviated liver hepatosteatosis and improved insulin sensitivity in part, via a macrophage IL-10 dependent mechanism." (PMID 26340260, 2015). "In support of this, ZIP14 down-regulation was correlated with the expression of several cytokines produced in unhealthy adipose tissue as part of the inflammatory response in obesity, i.e., TNF-α and IL-10." (PMID 26623077, 2015). "In order to investigate the role of a broad range of pro- and anti-inflammatory cytokines in obesity, serum levels of TNF-α, IFN-γ, IL-2, IL-4, IL-5, IL-10, IL-12, IL-13, and GM-CSF were compared between obese and non-obese participants." (PMID 25781614, 2015). "Realizing that obesity is a chronic inflammatory state, we also explored the baseline and post-intervention levels of cytokines such as TNF-alpha, IL-6, IL-10, and PAI-1." (PMID 26611872, 2015). "As expected, significantly elevated plasma leptin and suppressed adiponectin, a typical adipokine phenotype of obesity, were shown in Class III obese subjects, as was the inflammatory profile of much higher levels of plasma hsCRP but lower IL10." (PMID 23342053, 2013). "Higher levels of the IL-1β/IL-10 ratio were observed in the subgroups with obesity than in the normal weight subgroups, regardless of gender." (PMID 41602164, 2026). "At the same time, the negative correlation of IL-10 with BMI (r = −0.52) emphasizes the reduction of anti-inflammatory mechanisms in obesity, which contributes to metabolic disorders." (PMID 40218200, 2025). "Together with the increases in HDL cholesterol and IL-10 and the reductions in LDL cholesterol and IL-6, these adaptations highlight the comprehensive cardiometabolic and anti-inflammatory benefits of web-based HIIT in middle-aged men with obesity." (PMID 41367390, 2025). "Obesity induced by high-fat diet results in heightened inflammation in the pancreas, liver, and WAT when the spleen is absent; this response appears to be dependent of anti-inflammatory IL-10 derived from splenic tissue." (PMID 40276696, 2025). "In the case of IL-10 and IL-17, the psoriatic mechanisms govern the statistically increased circulatory levels rather than the induced obesity." (PMID 40869018, 2025).
Obesity (continued). "As observed in other tissues, obesity also induces inflammation in the testes, mainly through the overexpression of TNF-α, inducible nitric oxide synthase (iNOS), and IL-1β, accompanied by the underexpression of IL-10." (PMID 40002337, 2025). "After infection, the results of IFN-γ, TNF-α, IL-4, IL-10 and IL-12 p70 in obesity + infection group were not obviously different from those in normal + infection group." (PMID 38185681, 2024). "In addition, chronic systemic inflammation is recognized as part of insulin resistance syndrome, T2DM, and obesity and is characterized by increased IL-6 and CRP levels, as well as decreased levels of adiponectin (ADIPOQ) and IL-10." (PMID 39408723, 2024). "Interleukin-10 (IL-10) was significantly increased in postmenopausal women with obesity and T2DM but not in men." (PMID 39575382, 2024). "The oral administration of Bifidobacterium longum NK49, Lactobacillus plantarum NK3, and Bifidobacterium longum PI10 improved obesity in mice by improving intestinal barrier integrity via glucagon-like peptide 1 (GLP1) and IL-10 induction, modulating immune cells, and lowering TNF-α expression." (PMID 38534735, 2024). "Elevated anti-inflammatory cytokines (IL-4 and IL-10) and neurotrophic factors (BDNF, IGF-1) in silymarin-treated mice suggest that silymarin may offer neuroprotective benefits by mitigating obesity-related neuroinflammation." (PMID 39624169, 2024). "Considering the link between obesity and inflammation, we aimed to examine the early effects of bariatric surgery (laparoscopic sleeve gastrectomy) on inflammatory and anti-inflammatory cytokines (TNF-α, IL-6, IL-10)." (PMID 39180618, 2024). "Individuals with obesity exhibit markedly reduced immunological tolerance, leading to excessive production of inflammatory mediators such as IL-6, TNF-α, IL-1β, and IFN-γ, alongside a significant decrease in anti-inflammatory cytokines like IL-4 and IL-10." (PMID 38840158, 2024). "Among chronic disorders, obesity is reported to be a noteworthy promoter of inflammatory status, characterized by an increase in tumor necrosis factor-α (TNF-α), interleukin 6 (IL6), and interleukin 10 (IL10) production." (PMID 38721147, 2024). "Increased TLR expression in mice with T1DM without associated obesity was accompanied by increased NF-κB, IL-6, IL-12, and TNF-α levels and decreased anti-inflammatory cytokine IL-10 levels." (PMID 39408723, 2024). "IAA, has been reported to be produced by the flora from tryptophan metabolism and can alleviate inflammation related to alcoholic liver disease and obesity by directly or indirectly regulating the balance between proinflammatory and anti-inflammatory cytokines (TGF-β, TNF-α, IL-10, and IL-22)." (PMID 37495941, 2023). "Plausibly, TNF-α itself could modulate IL10 upregulation by KBs, as suggested by studies reporting that IL-10 is up-regulated by TNF-a in vitro as well as in obesity both in humans and rodents." (PMID 37508009, 2023). "Our data also showed significant increase in the levels of TNF-β, IL-5, PTX3 in T1DM, T2DM and obesity groups in comparison to infected control group, whilst the levels of FOXP3 and IL-10 were increased in the infected groups in comparison to their noninfected controls." (PMID 37296126, 2023). "A large body of evidence suggests that inflammatory cytokines such as TNF-α, IL-1β, and IL-6 not only induce systemic insulin resistance but also affect lipid metabolism, whereas the presence of IL-10 effectively improves insulin sensitivity and HFD-induced obesity." (PMID 38162665, 2023). "The higher transcription of mRNA FOXP3 and IL-10 (Treg markers), accompanied by a high transcription of TBX21 and IFNG (Th1 markers), GATA3 and IL-4 (Th2 markers) indicated the inflammatory status in the group with obesity and an altered Treg function." (PMID 37215211, 2023).
Obesity (continued). "Obesity is related to an increased production of cytokines for the pro-inflammatory response (e.g., leptin, TNF-α, and IL-6) and a decreased secretion of adipokines that protect inflammatory response (e.g., adiponectin and IL-10)." (PMID 37821991, 2023). "Oligofructose supplementation could reverse obesity-induced GMB changes, reduce IL-12 and MCP-1, and increase IL-10." (PMID 37180142, 2023). "Further, obesity can induce B cell defects, including a lower frequency of regulatory B cells (with phenotypes CD19+ CD27+ CD38High, CD19+ CD24High CD38High, and CD19+ CD24High CD38High IL-10+), in response to infection." (PMID 35795152, 2022). "In this way, the present study demonstrated that combined exercise training increased the plasma levels of adiponectin in non-obese and obesity grade I women and the plasma levels of IL-10 in non-obese, overweight, and obesity grade I women." (PMID 36160852, 2022). "WAT IL-10 levels are higher in women with obesity and T2D, but not in men and this effect is primarily attributed to obesity per se." (PMID 36313784, 2022). "While IL-10 secretion was similar in healthy non-obese men and women, it was significantly increased in women with obesity and T2D compared to controls, but this increase was absent in men." (PMID 36313784, 2022). "During obesity, neutrophils have high neutrophil elastase, neutrophil alkaline phosphatase, myeloperoxidase, IL-6, IL-1β, IL-12, IL-8, and TNF-α, and low expression of IL-10, which favors activation of M1 macrophages and development of chronic inflammation." (PMID 36230963, 2022). "In men, the amounts of IL-10-secreting cells were not different in the healthy non-obese compared to individuals with obesity and T2D." (PMID 36313784, 2022). "The correlations between gut microbiota (based on OTUs) and obesity related indexes (including body weight gain, percent of epididymal fat weight, the levels of TG, TC, HDL, LDL, TNF-α, IL-6, IL-10, and IL-4) were investigated using the Pearson correlation analysis." (PMID 35807812, 2022). "In contrast, IL-10 was lower in serum of men with obesity and T2D compared to non-obese healthy men." (PMID 36313784, 2022). "Spleen-derived IL-10, a potent anti-inflammatory cytokine, may protect against the development of NAFPD, but obesity reduces IL-10 production in HFD-fed mice." (PMID 35327494, 2022). "Of note, we also observed an increase in anti‐inflammatory cytokines (e.g., IL‐10 and TGF‐β1) in the CM of hASCs modified by aging or obesity, which fits with the finding that age‐related inflammation is linked to the presence of some anti‐inflammatory factors in the hASC niche." (PMID 35811457, 2022). "Similarly, among the 15 anti-inflammatory organokines, 7 (adiponectin, Omentin-1, ZAG, SFRP5, CTRP3, IL-10, and DEL-1) showed reduced levels and 8 (LCN2, VASPIN, IL-1RA, FGF21, GDF15, MANF, Irisin, and IL-6) showed elevated levels in patients with obesity." (PMID 35909571, 2022). "After adjusting for sex, age, hypertension, blood lipid concentration, and obesity, the level of TNF-α in the case group was higher than that in the control group, following that of IL-10 and IL-4, which indicated that an increased plasma level of TNF-α was significantly associated with sarcopenia." (PMID 36160136, 2022). "Upon obesity, ATMs with low IL-10 production failed to inhibit hepatic gluconeogenesis, resulting in high HGP and hyperglycemia." (PMID 36091076, 2022). "Periodontitis increased tumor necrosis factor-α level of lung tissues under LF, while IL-10 was not affected by obesity regardless of periodontitis." (PMID 36060644, 2022). "Although we did not observe a direct effect of E1 or any other tested sex hormone on IL10 expression in WAT SVF or THP-1 macrophages in vitro, we cannot exclude that sex hormones (and E1 in particular) are playing a role in obesity-related IL-10 upregulation in women in vivo." (PMID 36313784, 2022). "This indicates that obesity/T2D has different impacts on circulating and WAT IL-10." (PMID 36313784, 2022).
Obesity (continued). "We had observed that IL10-MSCs treatment had a protective effect on obesity and insulin resistance in HFD-fed mice, so we further explored whether IL10-MSCs treatment could alleviate chronic inflammation under HFD feeding." (PMID 35715850, 2022). "Therefore, IFNβ-induced IL-10 is a major mechanism by which IRF3 inhibits macrophage inflammatory activation and adipose tissue inflammation in obesity." (PMID 34091599, 2021). "The study aimed to follow up on the changes in the peripheral CD4+ T lymphocytes and the pro-inflammatory cytokines; IL-6, TNF-alpha, MCP-1, and IL-10 at baseline and 12 weeks post-surgical intervention by the laparoscopic gastric sleeve (LGS) in morbidly obese patients (class III obesity subjects)." (PMID 33981153, 2021). "In this context, it was reported by several authors a negative relationship between obesity and IL-10 levels; in some cases, this cytokine correlated positively with energy homeostasis and negatively with insulin resistance." (PMID 34568404, 2021). "In our present study, we found that after the construction of obesity-induced IR animal model, in total CD4+ T cells, Treg cells were reduced, Th17 cells were increased, levels of markers TGF-β1 and IL-10 were downregulated, and those of IL-17 and IL-6 were upregulated." (PMID 33781239, 2021). "Adipose tissue hyperplasia during obesity induces the secretion of adipocytokines such as leptin, interleukin-6 (IL-6), interleukin-1β (IL-1β), IL-10, TNF-α, monocyte chemo-attractant protein-1, and plasminogen activator inhibitor-1, which are responsible for obesity-related inflammation." (PMID 33946303, 2021). "During obesity, the pro-inflammatory skewing of immune cells favors the release of cytokines such as TNF and IFNγ, coupled with a reduction in IL-10, IL-17, and IL-22, resulting in reduced expression of epithelial tight junction proteins, mucin, and antimicrobial proteins such as RegIIIγ2,33." (PMID 33972511, 2021). "Previous studies have shown that expression of IL-10 and IL-13 in WAT cells may be elevated by obesity-induced ER stress." (PMID 33717200, 2021). "Nevertheless, studies on the interplay between obesity and IL-10 expression have not been conducted thoroughly." (PMID 31986244, 2020). "Myeloid-specific deletion of three clusters of miR-17~92 family miRNAs twisted ATMs toward a spontaneously inflammatory phenotype characterized by diminished IL-10 and elevated TNF, leading to disrupted adipose homeostasis evidenced by obesity and compromised glucose tolerance." (PMID 33150865, 2020). "Blood and tissue inflammatory cytokine levels including either TNF-α, IL-1b, IL-6, IL-10, or MIP-2a were also increased with obesity in 22 of 30 cases and may have contributed to inflammatory organ injury and worsened survival." (PMID 32211204, 2020). "Although obesity is considered a low-grade systemic inflammatory state, in the present study, we did not observe differences in us-CRP and in most of the cytokines analysed in blood serum (IL-6, TNF-α, IL-1β, IL-10, MCP-1 and leptin)." (PMID 33489104, 2020). "Based on their previous findings that mice lacking IL10 exhibit enhanced thermogenesis and are protected from diet-induced obesity, they looked for this beige adipocyte population in IL10 receptor knockout mice and expectedly found it in a high proportion." (PMID 32635651, 2020). "In addition, work in mice found that Bacteroides uniformis improves immune defense mechanisms, which are impaired in obesity, by decreasing TNF-α production and increasing IL-10 production." (PMID 32917289, 2020). "The recruited ATMs secrete both anti-inflammatory (interleukin-10 (IL-10) and IL-1) and pro-inflammatory (tumor necrosis factor-α (TNF-α), IL-6, and IL-1β) cytokines, suggesting they can serve both a protective and harmful role in obesity." (PMID 32133436, 2019). "We found lower IL-10 levels in individuals with obesity (with and without BED) compared to AN and HCs, confirming previous findings." (PMID 31450770, 2019).